SPINK1 (serine peptidase inhibitor Kazal type 1)
Diseases named in the same sentence as SPINK1 in open-access papers (continued):
Sharing a sentence is not in itself a finding about the gene and the disease.
cancer (continued). "Some genes (e.g. SPINK1 in MAY and ANO4, KCTD8, COL15A1, and KCNH1 in ZMA) are related to cancer and skin properties and may have played a role in adaptation to Mayotte and Madagascar climates by increasing tolerance to thermal stress, humidity, and UV exposition." (PMID 35137043, 2022). "SPINK1 expression was specifically detected in a subset of ETS rearrangement-negative cancers." (PMID 33916984, 2021). "Thus, our data implies that SPINK1 represents one of the major TME-derived soluble factors precisely reflecting the development of an in vivo SASP and can be exploited to assess the SASP magnitude in cancer patients." (PMID 30333494, 2018). "Our data suggest that the resistance-antagonizing effects of SPINK1-targeting strategy are not restricted to a specific cancer type, but could be applicable in a pan-cancer manner." (PMID 30333494, 2018). "Our results not only provide a rationale for the development of humanized mAbs to SPINK1, but imply the technical feasibility of restraining cancer resistance by delivering a panel of humanized mAbs against the key SASP factors, to significantly improve therapeutic outcome in cancer clinics." (PMID 30333494, 2018). "In the PZ cancer group, a significant difference was not shown for the BCR‐free survival rate among the three subgroups, ERG‐/SPINK1‐, ERG‐/SPINK1+, and ERG+/SPINK1‐ (P = .39)." (PMID 35475132, 2021). "To determine whether or not the expressions of SPINK1 were related to the immune microenvironment of HCC, we accessed the TCGA database and downloaded the data of 374 cancer patients who were still alive at the time of the study." (PMID 38093163, 2023). "In our analyses, the group with a high expression of SPINK1 did not reveal a positive correlation with TMB, which may increase the likelihood of ICB response, as described by other researchers in cancer control." (PMID 35924241, 2022). "In contrast, the overexpression of SPINK1 in stromal cells did not confer survival advantage when cells were exposed to increasing concentrations of genotoxic drugs such as BLEO, suggesting different survival mechanisms between cancer and stromal cells." (PMID 30333494, 2018). "ERG and SPINK1 expressing cancers do not appear to be strictly mutually exclusive molecular subtypes, although SPINK1 expression does appear to be uncommon in ERG-expressing cancers." (PMID 26172920, 2015).
infection (8 papers, 2010 to 2024). The state of being infected such as from the introduction of a foreign agent such as serum, vaccine, antigenic substance or organism. "In addition, severe infections and tissue destruction cause elevation of SPINK1 in serum and urine, suggesting that it is an acute phase protein of the immune system." (PMID 32793510, 2020).
bacterial infection (1 paper, 2023). "Enrichment analysis showed that SPINK1+ HCC and APOA1+SPINK1+PLA2G2A+ HCC cells were significantly involved in bacterial infection-related pathways." (PMID 37333982, 2023).
kidney disease (1 paper, 2023). "We categorized patients based on molecular markers and found that the ERG+/SPINK1+ subgroup had higher postoperative kidney disease stages and serum creatinine levels compared to the ERG+/SPINK1− subgroup, suggesting a connection between SPINK1 overexpression and kidney function." (PMID 37894380, 2023).
SPINK1 also shares sentences with these, for which no sentence is quoted: hypertriglyceridemia (6 papers); adenocarcinoma (4); autoimmune pancreatitis (3); metabolic disorder (3); colorectal (2); cyst (2); gallstones (2); genetic conditions (2); head and neck cancer (2); hypercalcaemia (2); Lynch syndrome (2); pancreatic ductal adenocarcinoma (2); type II diabetes (2); Anxiety (1); Ataxia (1); Autoimmunity (1); autosomal dominant Parkinson disease 8 (1); autosomal recessive disease (1); breast tumors (1); cardiovascular diseases (1); cervical adenocarcinoma (1); chronic kidney disease (1); colorectal polyps (1); endocrine system disorder (1); endometrial cancer (1); esophageal squamous cell carcinoma (1); Failure to thrive (1); Familial adenomatous polyposis (1); female sterility (1); functional dyspepsia (1).
A further 28 diseases each share a sentence with SPINK1 in 1 paper.